SIRT5 (sirtuin 5)
Diseases named in the same sentence as SIRT5 in open-access papers (continued):
Sharing a sentence is not in itself a finding about the gene and the disease.
melanoma (11 papers, 2019 to 2025). A malignant, usually aggressive tumor composed of atypical, neoplastic melanocytes. "The importance of Sirtuin 5 (SIRT5) in the progression of melanoma, including uveal melanoma, has been demonstrated." (PMID 39199614, 2024). "Similar with our result, a previous study has showed that c-myc is a SIRT5-dependent gene in melanoma." (PMID 38532359, 2024). "Transcriptomic investigations show that SIRT5 is essential for melanoma cells to maintain balanced gene expression." (PMID 36980194, 2023). "Specifically, SIRT5 promotes cancer development in both Braf/Pten-driven autochthonous melanoma and xenograft mouse models of melanoma." (PMID 36980194, 2023). "SIRT5 is the only known mitochondrial desuccinylates, belonging to the evolutionarily conservative sirtuin family, and is highly expressed in breast tumors, melanoma, and renal cell carcinoma." (PMID 38585637, 2024). "SIRT5 regulates histone modifications, inhibiting melanoma growth when dysfunctional." (PMID 39494561, 2024). "In addition, SIRT5 was essential for tumordevelopment in both melanoma mouse xenografts and the autochthonous BRAF PTEN-driven melanoma mouse model." (PMID 35802779, 2022). "SIRT5 promotes melanoma cell survival partially through PDC." (PMID 34930316, 2021). "SIRT5 is responsible for the proliferation and survival of BRAF-mutant melanoma cells through repressing apoptosis as a consequence of chromatin modification and expression of survival factors such as MITF and c-Myc." (PMID 39935431, 2025). "However, there is also evidence that SIRT5 is not required for BRAFV600E melanoma growth in vivo and did not sensitize BRAF-mutant melanoma to BRAF inhibitor therapy." (PMID 39935431, 2025).
glioma (10 papers, 2015 to 2025). A benign or malignant brain and spinal cord tumor that arises from glial cells (astrocytes, oligodendrocytes, ependymal cells). "Higher levels of SIRT5 expression are linked to a more favorable prognosis for glioma patients, suggesting a protective effect against tumor progression." (PMID 40710366, 2025). "We found that higher SIRT5 expression levels were associated with a favorable prognosis in glioma patients." (PMID 39201811, 2024). "VSNL1, the gene highly upregulated upon high SIRT5 expression in gliomas, encodes visinin-like protein 1 (VILIP-1)." (PMID 39201811, 2024). "ROC curve analysis was performed and >80 percent diagnostic sensitivity was measured in case of SIRT3 and SIRT5 genes in glioma patients." (PMID 36809279, 2023). "The strong association between low SIRT5 expression and aggressive glioma characteristics suggests that SIRT5 could serve as a valuable biomarker for assessing glioma grades." (PMID 39201811, 2024). "A few studies have also suggested that SIRT5 expression may be reduced in glioma samples, with higher expression levels associated with improved patient survival." (PMID 39201811, 2024). "These innovations could lead to more precise and convenient diagnostic methods, enhancing the utility of SIRT5 expression in the diagnosis and prognostic prediction of gliomas." (PMID 39201811, 2024). "SIRT5 knockdown significantly reduced glioma cell proliferation and enhanced sensitivity to ferroptosis." (PMID 40195331, 2025). "Our findings demonstrate that SIRT5 expression is elevated in glioma cells both in vitro and in vivo." (PMID 40195331, 2025). "In glioma patients, SIRT5 is significantly downregulated compared with healthy controls, with a highly significant p-value of less than 0.0001." (PMID 40710366, 2025). "SIRT5’s regulation of mitochondrial metabolism and its involvement in synaptic remodeling further highlight its significance in glioma biology." (PMID 40710366, 2025). "SIRT5 has been shown to contribute to cisplatin resistance in ovarian cancer through modulation of the Nrf2/HO-1 pathway and to suppress tumor growth in gliomas by regulating mitochondrial metabolism." (PMID 40710366, 2025). "SIRT5 is also found to be significantly correlated with pathways involved in synaptic remodeling, indicating that SIRT5’s influence extends beyond metabolism, potentially affecting neuroplasticity and the brain’s structural adaptations in response to glioma." (PMID 40710366, 2025). "Collectively, this study highlights the critical role of SIRT5 in promoting glioma progression via metabolic regulation and ferroptosis insensitivity, offering a potential therapeutic target for glioma treatment." (PMID 40195331, 2025). "In conclusion, this study advances our understanding of SIRT5’s role in glioma biology and its potential as a prognostic biomarker." (PMID 39201811, 2024). "Our findings suggest a possible link between SIRT5 expression and immune response regulation in gliomas." (PMID 39201811, 2024). "To investigate the biological function of SIRT5 in glioma, we performed a series of experiments using single-cell analysis, in vitro assays, and in vivo xenograft studies." (PMID 39201811, 2024). "We separately identified differentially expressed genes (DEGs) between high- and low-SIRT5 gliomas in the TCGA and CGGA datasets." (PMID 39201811, 2024). "Our investigations revealed that decreased SIRT5 expression correlates with poorer glioma patient survival." (PMID 39201811, 2024). "Our findings underscore the necessity for further in-depth investigation into the diverse functions of SIRT5 in glioma progression, particularly its impacts on mitochondrial metabolism, immune modulation, and synaptic remodeling." (PMID 39201811, 2024). "To further elucidate the biological functions of SIRT5 in gliomas, we conducted a comprehensive analysis of gene expression data from bulk tumor samples." (PMID 39201811, 2024).
glioma (continued). "In this study SIRT5 is found to be downregulated in glioma patients as compared to the healthy controls depicting its role as a tumor suppressor." (PMID 36809279, 2023). "In glioma patients, SIRT5 is significantly downregulated compared with healthy controls, suggesting it may act as a tumor suppressor in gliomas." (PMID 40710366, 2025). "In this study, we investigate the role of SIRT5 in glioma and its corresponding mechanisms." (PMID 40195331, 2025). "Collectively, our findings strongly suggest a tumor-suppressive function of SIRT5 in gliomas." (PMID 39201811, 2024). "We first investigated the clinical significance of SIRT5 in glioma patients." (PMID 39201811, 2024). "Notably, SIRT5 was downregulated in recurrent and secondary gliomas, as well as gliomas with specific genetic characteristics, such as the IDH wildtype, unmethylated MGMT, and 1p19q non-codeletion." (PMID 39201811, 2024). "Collectively, these results suggest that SIRT5 may regulate not only glioma cell growth but also the activities of synapses and immune responses in gliomas." (PMID 39201811, 2024). "Future studies are needed to identify SIRT5 target proteins in gliomas and how these mitochondrial modifications may impact metabolism and energy homeostasis." (PMID 39201811, 2024). "The present study aimed to investigate the functional role of SIRT5 in glioma pathogenesis." (PMID 39201811, 2024). "In addition, the Kaplan–Meier curve showed that SIRT1, SIRT3, and SIRT5 were closely associated with OS, DSS, and PFI of glioma patients, and other SIRT family members are related to the prognosis of glioma patients to varying degrees." (PMID 36568393, 2022). "This downregulation suggests that SIRT5 may act as a tumor suppressor in gliomas." (PMID 40710366, 2025). "Our analysis revealed that high SIRT5 expression was associated with improved patient outcomes, including a longer duration of disease-specific survival (DSS), overall survival (OS), progression-free interval (PFI), and progression-free survival (PFS) in Grade 2–4 glioma patients." (PMID 39201811, 2024). "Thus, the current study is designed to investigate expression level of SIRT3, SIRT4, SIRT5 and associated genes SOD1, SOD2, OGG1-2α, PARP1, GDH and HIF1α in glioma patients and to find out whether this expressional deregulation effects the risk of glioma." (PMID 36809279, 2023). "Clinically, we reveal a positive correlation between SIRT5 and BCAT1 levels in glioma samples, with higher expression levels predicting more advanced glioma grades and poorer clinical outcomes." (PMID 40195331, 2025). "SIRT1, SIRT3, SIRT5, and SIRT7 are often overexpressed and promote glioma cell proliferation, stemness, therapy resistance, and metabolic adaptation." (PMID 40710366, 2025). "Next, WGCNA was used to identify gene modules highly correlated with SIRT5 expression in the TCGA and CGGA glioma samples." (PMID 39201811, 2024). "Results analysis showed significant down-regulation of SIRT4 (p = 0.0337), SIRT5 (p<0.0001), GDH (p = 0.0305), OGG1-2α (p = 0.0001), SOD1 (p<0.0001) and SOD2 (p<0.0001) in glioma patients compared to controls." (PMID 36809279, 2023). "Unlike SIRT3, which is upregulated in glioma patients, SIRT5’s downregulation highlights the different roles that these sirtuins play in cancer biology." (PMID 40710366, 2025). "Present study was purposed to figure out the expression level of mitochondrial sirtuins (SIRT3, SIRT4, SIRT5) and related genes (GDH, OGG1-2α, SOD1, SOD2, HIF1α and PARP1) in 153 glioma tissue samples and 200 brain tissue samples from epilepsy patients (taken as controls)." (PMID 36809279, 2023).
liver cancer (10 papers, 2019 to 2025). An epithelial or non-epithelial malignant neoplasm that arises from the liver. "However, upregulated SIRT5 in liver cancer tissues was found to be associated with favorable prognosis." (PMID 31456942, 2019). "SIRT5 has dual roles in promoting or suppressing tumors, with its expression being significantly downregulated in liver cancer tissues." (PMID 40557149, 2025). "SIRT5 deacetylates K120 of Vimentin, downregulates its activity and inhibits liver cancer cell migration." (PMID 39979670, 2025). "In this study, we found that the expression of the de-succinylase SIRT5 is reduced in human liver cancer tissues, which promotes lysine succinylation in HCC." (PMID 40557149, 2025). "In this study, we found that the expression of SIRT5 protein is decreased in human liver cancer tissues and HCC mice, and the reduced expression of SIRT5 is associated with elevated succinylation levels of CS." (PMID 40557149, 2025). "Since miR-299-3p targets SIRT5, it prevents liver cancer cells from migrating, invading, or proliferating." (PMID 36059797, 2022). "Although these results when weighed against its relatively low‐expression in HCC tissues and cell lines seems to beyond common sense, these findings are contributing to revealing the real function of SIRT5 in liver cancer." (PMID 32596968, 2020). "Specifically, the downregulation of SIRT5 was observed in head and neck squamous cell carcinoma, liver cancer, and endometrial carcinoma, which highlight the tumor-suppressive role of SIRT5." (PMID 31456942, 2019). "In mouse liver cancer tissues, SIRT5 expression was reduced while CS expression was increased." (PMID 40557149, 2025). "SIRT5 can deacetylate Cytc, increase the distribution of Cytc in mitochondria to inhibit mitochondrial apoptosis, and is also a potential marker and drug target for the diagnosis and treatment of liver cancer." (PMID 39979670, 2025). "Finally, we also found that SIRT5 can reverse the high succinylation of CS and induce apoptosis in liver cancer cells, exerting an anti-tumor effect." (PMID 40557149, 2025). "Previous studies have reported the upregulation of SIRT5 gene in breast, ovarian and liver cancer." (PMID 36809279, 2023). "SIRT5 can regulate bile acid metabolism and inhibit immune escape of liver cancer cells." (PMID 36568393, 2022). "In short, SIRT5 plays the role of an inhibitor in liver cancer." (PMID 32596968, 2020). "SIRT5 has been proven to be involved in tumorigenesis and drug resistance in many cancers, but opposite tumor-suppressor roles have also been found in various tumor treatment models, including liver cancer, Kras-induced pancreatic cancer, renal cell carcinoma, and acute promyelocytic leukemia." (PMID 38485947, 2024). "Moreover, ROC analysis demonstrated that the expression of CS and SIRT5 could distinguish HCC from normal tissue with high accuracy, thereby reinforcing the rationale for exploring their mechanistic interplay in mitochondrial metabolism and apoptosis regulation in liver cancer cells." (PMID 40557149, 2025).
prostate carcinoma (10 papers, 2020 to 2025). A carcinoma that arises from epithelial cells of the prostate gland. "Overall, these results indicate that SIRT5 expression is closely associated with prostate cancer progression." (PMID 33103371, 2020). "In the cBioPortal database, we found that the SIRT5 gene is mutated in prostate cancer and that most of these mutations are deep deletions and missense mutations." (PMID 33103371, 2020). "However, there was no apparent statistical significance in our data; consequently, we ignored the effect of SIRT5 gene mutations on prostate cancer." (PMID 33103371, 2020). "In prostate cancer, SIRT5 expression is significantly reduced, and a correlation between decreased SIRT5 levels and reduced patient survival has been established." (PMID 39944690, 2025). "For example, lactate dehydrogenase A (LDHA) is desuccinylated at K118 by SIRT5, downregulates its activity and inhibits migration and invasion of prostate cancer (PCa) cells." (PMID 39979670, 2025). "In the case of prostate cancer, one study indicated that SIRT5 promotes cancer cell proliferation and migration by targeting acetyl‐CoA acetyltransferase 1 (ACAT1)." (PMID 39215785, 2025). "SIRT5 expression is also reduced in androgen-independent PC-3 and PC-3M prostate cancer cells, with larger reductions occurring in more advanced stages of the disease." (PMID 36980194, 2023). "SIRT5 is also significantly expressed in prostate cancer, where it activates acetyl-CoA acetyltransferase 1 (ACAT1) and induces a mitogen-activated protein kinase (MAPK) pathway." (PMID 36980194, 2023). "Since ACAT1 negatively regulates the MAPK signaling pathway, Peck and Shulze concluded that SIRT5 promotes the proliferation, invasion, and migration of prostate cancer via the downregulation of ACAT1 protein levels." (PMID 36291902, 2022). "The findings of these two recent studies indicate that the tumor-suppressing effect of SIRT5 in prostate cancer increases as the prostate cancer progresses but reduces at the point of secondary metastasis (from the bone to other tissues)." (PMID 36291902, 2022). "A recent study has identified another post-translational mechanism of LDHA regulation via protein sirtuin 5 (SIRT5) in prostate cancer." (PMID 36551514, 2022). "Nevertheless, further studies are required to corroborate the current findings and investigate the consequences of the modulation of other targets by SIRT5 in prostate cancer." (PMID 36291902, 2022). "In MTS and colony formation assays, it was evident that high expression of SIRT5 promoted proliferation and colony formation in prostate cancer cells." (PMID 33103371, 2020). "Cell proliferation and colony formation experiments were performed to assess the effect of SIRT5 expression on the proliferation ability of prostate cancer cells." (PMID 33103371, 2020). "With transwell experiments, we showed that high expression of SIRT5 protein promoted prostate cancer cell migration." (PMID 33103371, 2020). "To study the expression of SIRT5 in human prostate cancer tissues, we performed immunohistochemical experiments on 57 randomly selected prostate tissue sections." (PMID 33103371, 2020). "Statistical analysis of 57 tissue sections showed that the expression of SIRT5 was related to the Gleason score of prostate cancer." (PMID 33103371, 2020). "Using the cBioPortal, Human Protein Atlas databases, Oncomine and immunohistochemistry experiments, we showed that SIRT5 was expressed in prostate cancer tissue and cell lines at both the mRNA and protein levels." (PMID 33103371, 2020). "LDHA-K118su, a SIRT5 substrate markedly elevates invasion and migration by prostate cancer cells." (PMID 37705968, 2023). "Because succinylated Lys118 positively regulates LDHA enzymatic activity, it is not surprising that low SIRT5 expression was linked to prostate cancer progression." (PMID 36551514, 2022).
prostate carcinoma (continued). "However, in contrast, recent studies have revealed that SIRT5 expression is downregulated in advanced prostate cancer, suggesting that SIRT5 downregulation is dependent on the progression or stage of the prostate cancer cells." (PMID 36291902, 2022). "Interestingly, the authors further revealed that SIRT5-facilitated downregulation of the PI3K/AKT/NK-kB pathway reduced as the prostate cancer metastasized from the bone to other tissues." (PMID 36291902, 2022). "There are few studies on the mechanistic roles of SIRT5 in prostate cancer." (PMID 36291902, 2022). "In prostate cancer, SIRT5 is responsible for increased lysine 118 desuccinylation of LDHA." (PMID 36551514, 2022). "Examination of the databases indicated SIRT5 gene mutations in prostate cancer; however, these mutations had no significance in the prognosis of the disease." (PMID 33103371, 2020). "Therefore, to explore the diagnosis and treatment of prostate cancer, we investigated the effect of SIRT5 on prostate cancer." (PMID 33103371, 2020). "To understand how SIRT5 protein affects prostate cancer cells, we performed Western blot analyses." (PMID 33103371, 2020). "Therefore, we concluded that SIRT5 expression was related to the prostate cancer Gleason score." (PMID 33103371, 2020). "Overexpression of SIRT5 reduces LDHA-K118 succinylation, inhibiting the migration and invasion of prostate cancer cells and alleviating disease progression." (PMID 39944690, 2025). "When SIRT5 is overexpressed, the levels of active and functional downstream proteins of MAPK signaling pathway increase, promoting prostate cancer growth." (PMID 39979670, 2025). "The authors further demonstrated that SIRT5 decreased the protein levels of acetyl-CoA acetyltransferase 1 (ACAT1), a promoter of prostate cancer." (PMID 36291902, 2022). "A recent study demonstrated that SIRT5 promotes the proliferation and migration of LNCaP and PC3 prostate cancer cells." (PMID 36291902, 2022). "Conversely, a more recent study demonstrated that SIRT5 expression reduces the migration and invasion of PC3 prostate cancer cells." (PMID 36291902, 2022). "This was found to occur via SIRT5 desuccinylation of LDHA to reduce its activity, culminating in the growth reduction and survival of prostate cancer cells." (PMID 36291902, 2022). "Overall, these results demonstrate that SIRT5 regulates the MAPK signalling pathway through ACAT1 and has a tumour‐promoting role in prostate cancer." (PMID 33103371, 2020). "We determined that ACAT1 can regulate the MAPK signalling pathway; therefore, we believe that SIRT5 regulates the MAPK signalling pathway through ACAT1, thereby promoting prostate cancer." (PMID 33103371, 2020). "In addition, SIRT5 enhances the MAPK signaling pathway through acetyl-CoA acetyltransferase 1 (ACAT1), increasing the ability of prostate cancer cells to proliferate, migrate, and invade." (PMID 39979670, 2025). "Sirtuin 5 (SIRT5) is a NAD+‐dependent class III protein deacetylase, and its role in prostate cancer has not yet been reported." (PMID 33103371, 2020).